MMP2 (matrix metallopeptidase 2)
Diseases named in the same sentence as MMP2 in open-access papers (continued):
Sharing a sentence is not in itself a finding about the gene and the disease.
lymphoid tumor (1 paper, 2000). "The currentstudy was designed to determine the expression and production of MMP-2 (gelatinase A)and MMP-9 (gelatinase B) by human lymphoid tumor cells." (PMID 11097203, 2000).
macular edema (1 paper, 2022). "Therefore, although the exact mechanism remains to be elucidated, increased MMP-2 and -9 expression affects various inflammatory processes, leading to macular edema which can cause severe visual impairment." (PMID 36180575, 2022).
marasmus (1 paper, 2022). The lack of sufficient energy or protein to meet the body's metabolic demands, as a result of either an inadequate dietary intake of protein, intake of poor quality dietary protein, increased demands due to disease, or increased nutrient losses. "To further investigate the role of ECM degradation on oedema in SM, we compared plasma MMP2 concentrations between children with kwashiorkor and marasmus." (PMID 35398787, 2022).
marginal zone B cell lymphoma (1 paper, 2016). "However, others have reported anetoderma arising from marginal zone B cell lymphoma in which MMP-9, but not MMP-2 or MMP-12, is expressed in infiltrating lymphocytes, suggesting some degree of pathogenic heterogeneity for this disease." (PMID 28116317, 2016).
mast cell tumors (1 paper, 2023). "The results obtained in studies on mast cell tumors show that in this case MMP-9 has greater diagnostic and prognostic significance, while the activity of MMP-2 varied depending on the degree of tumor differentiation, but not to such a significant extent." (PMID 37895400, 2023).
mesenchymal tumors (1 paper, 2001). "Discussion: These findings suggest that the MMP-inducer EMMPRIN and the extracellular matrix degrading systeminvolving the metalloproteinases MMP-2 and MT1-MMP is frequently activated in mesenchymal tumors." (PMID 18521441, 2001). "In thepresent study we investigated the expression and location of mRNAs for EMMPRIN, matrix metalloproteinase-2 (MMP-2),and membrane-type 1 matrix metalloproteinase (MT1-MMP) in mesenchymal tumors with different tendencies to recur ormetastasize." (PMID 18521441, 2001).
Mitral regurgitation (1 paper, 2015). An abnormality of the mitral valve characterized by insufficiency or incompetence of the mitral valve resulting in retrograde leaking of blood through the mitral valve upon ventricular contraction. "As a surrogate marker of mitral regurgitation, we tested the association of MMP2 variants by comparing allele frequencies of MVP patients who had surgery (n = 421) to the total sample of SU.VI.MAX Set 2 (n = 815)." (PMID 29371517, 2015).
mood disorder (1 paper, 2022). A cognitive disorder a disturbance in which the person's mood is hypothesized to be the main underlying feature. "Serum MMP-9 is found to be increased in MDD patients, while MMP-2 is decreased in MDD patients, indicating the involvement of MMP-2 and MMP-9 in mood disorders." (PMID 35996194, 2022).
muscle atrophy (1 paper, 2017). The loss of muscle tissue due to inactivity or disease. "Therefore, data on the balance between MMP-2 and TIMP-2 may provide useful information for evaluating the effects of low-frequency ES on reducing early-stage muscle atrophy and capillary regression in denervated muscles." (PMID 28497057, 2017).
Myalgia (1 paper, 2020). "Finally, we did not record any difference in the expression of MMP-2 and MMP-9 in patients who developed myalgia during statin treatment." (PMID 32111073, 2020).
myasthenia gravis (1 paper, 2022). Myasthenia gravis (MG) is a rare, clinically heterogeneous, autoimmune disorder of the neuromuscular junction characterized by fatigable weakness of voluntary muscles. "We evaluated the plasma levels of MMP-9 and MMP-2 and their tissue inhibitors TIMP-1 and TIMP-2 in a patients’ cohort with generalized myasthenia gravis (MG)." (PMID 36358365, 2022).
mycosis fungoides (1 paper, 2000). Classical mycosis fungoides is the most common type of mycosis fungoides (MF), a form of cutaneous T-cell lymphoma, and is characterized by slow progression from patches to more infiltrated plaques and eventually to tumors. "In patients with mycosis fungoides (MF), the expression of MMP-2 andMMP-9 mRNAs was significantly upregulated with advancing stage, in terms of lesions bothpositive for one of two mRNAs and with the greatest intensity of expression." (PMID 11097203, 2000).
neuromyelitis optica (1 paper, 2018). A rare inflammatory disease of the central nervous system characterized mainly by attacks of uni- or bilateral optic neuritis (ON) and acute myelitis. "The elevation of MMP-2 induced by IL-6 signaling was reported in the patients with BBB disruption of neuromyelitis optica." (PMID 29867440, 2018).
neurotoxicity (1 paper, 2022). Toxicity that causes injury to the central or peripheral nervous system or damages its function. "The third module included 3 genes in Neurotoxicity (Itpr1, Trim8, Lrp1), 4 in Blood–brain barrier (Ptpn23, Claudin5, Plectin, Mmp2) and 4 in Cognitive function (Slc8a3, Srf, Nf1, Ncam1)." (PMID 35899365, 2022).
neutropenia (1 paper, 2019). A decrease in the number of neutrophils found in the blood. "Accordingly, we examined the effect of neutropenia induced by means of the anti-Gr-1 monoclonal antibody on wound closure and MMP-2 expression." (PMID 31726690, 2019).
oncocytoma (1 paper, 2014). "Considering the average value of each molecule, the MMP-2 values were observed to be similar in the oncocytoma and ccRCC patients, however, the mean value was ~2-fold higher in the sera from the kidney disease patients compared with that of the control group." (PMID 24520285, 2014). "In the patients with oncocytoma, the MMP-2 values were positive in 3/4 (75%) of the specimens analyzed (range, 750–1,120 ng/ml; mean ± SD, 953±160 ng/ml), while in the patients with ccRCC, the values were positive in 12/16 (75%) of specimens (range, 697–1,949; mean ± SD, 1,027±314 ng/ml)." (PMID 24520285, 2014). "In the pathological specimens, the mean serum values of MMP-2 and TIMP-1 and -2 were similar in the ccRCC and oncocytoma patients, whereas the value for MMP-9 was 2-fold higher in the ccRCC patients compared with the oncocytoma patients." (PMID 24520285, 2014). "The mean values of MMP-2 and TIMP-1 were similar in the ccRCC and oncocytoma patients, whereas the mean values of MMP-9 were higher in the ccRCC patients compared with those of oncocytoma patients." (PMID 24520285, 2014). "The mean values for MMP-2 and -9 and TIMP-2 in the positive urine specimens were similar in the ccRCC and oncocytoma patients, whereas the mean value of TIMP-1 was higher in the ccRCC patients compared with that of the oncocytoma patients." (PMID 24520285, 2014). "Using a zymography technique, our previous study showed that MMP-9 is enhanced in the sera from ccRCC patients compared with that from oncocytoma patients, and that the most abundant lytic activity was at 92 kDa (MMP-9), whereas MMP-2 was present in reduced quantities." (PMID 24520285, 2014).
opisthorchiasis (1 paper, 2022). Infection with flukes of the genus Opisthorchis. "During the progression of chronic opisthorchiasis, the number of Mmp2+, Mmp9+, and TIMP1+ cells in the liver of infected hamsters significantly increased." (PMID 36355906, 2022).
oropharyngeal tumour (1 paper, 2014). "Samples from 61 patients diagnosed with oropharyngeal tumour were studied by immunohistochemistry against MMP-2, MMP-7, MMP-9 and MMP-13." (PMID 26019601, 2014).
osteitis (1 paper, 2025). "GV infection caused osteitis, leading to a notable increase in the expression of RANK, RANKL, TNF-α, IL-6, TRAP, and MMP-2 in the femur, accompanied by an increase in the number of TRAP+, TNF-α+, and RANK+ cells, while osteoprotegerin expression decreased." (PMID 40284791, 2025).
ovarian clear cell cancer (1 paper, 2012). An invasive malignant neoplasm that arises from the ovary and is characterized by a predominance of clear and hobnail malignant epithelial cells. "The influence of histological type has also been underlined in a study showing high level expressions of MMP-2 and MT1-MMP in ovarian clear cell carcinoma relative to other histotypes." (PMID 22200690, 2012).
Parkinsonism (1 paper, 2022). Characteristic neurologic anomaly resulting from degeneration of dopamine-generating cells in the substantia nigra, a region of the midbrain, characterized clinically by shaking, rigidity, slowness of movement and difficulty with walking and gait. "Altogether, our findings suggested that microglial MMP-2/-9 activation-mediated BBB dysfunction contributed to dopaminergic neurodegeneration in rotenone-induced mouse PD model, providing a novel view for the mechanisms of Parkinsonism." (PMID 35269933, 2022).
paroxysmal AF (1 paper, 2011). "Another interesting finding of our study was the remarkably increased serum MMP-2 of patients with paroxysmal AF of recent onset compared to both, individuals with SR and those with permanent AF." (PMID 22204652, 2011). "Patients with paroxysmal AF had higher levels of MMP-2 when compared to patients with permanent AF or controls (p < 0.001 for both comparisons)." (PMID 22204652, 2011).
pemphigoid (1 paper, 2021). "Interestingly, only the proenzymes of MMP-2/9 could be found in lesional skin and in blister fluid of pemphigoid patients which contrasts to the situation in experimental mice where both the pro- and active forms of MMP-9 were detected in lesional and non-lesional skin samples." (PMID 34680139, 2021). "Early work reported 72 and 92 kd collagenases, now known as MMP-2 and MMP-9, in skin blisters of pemphigoid patients." (PMID 34680139, 2021).
penile carcinoma (1 paper, 2015). "Campos and colleagues, using the conventional, subjective expression ‘scoring’ technique, have suggested that two members of the MMP family (MMP2 and MMP9) are over-expressed in penile carcinoma." (PMID 25901368, 2015).
perinatal asphyxia (1 paper, 2025). A disorder caused by a lack of blood flow or gas exchange to or from the fetus in the period immediately before, during, or after the birth process. "Our results suggest that MMP2 promoter polymorphisms may affect neurological outcomes after perinatal asphyxia." (PMID 41464177, 2025).
peripheral nerve injury (1 paper, 2017). Injury to a peripheral nerve. "Previous reports suggested that gene knockout of MMP-9 or administration of inhibitors for general or specific inhibition of MMP-9 and MMP-2 reduced nociceptive pain behaviors induced by peripheral nerve injury." (PMID 28199982, 2017).
pilomatricoma (1 paper, 2024). "In patients with bullous pilomatricoma, MMP-2- and MMP-9-positive cells had higher H-scores than those in patients with ordinary pilomatricoma." (PMID 38350760, 2024).
pleural malignant mesothelioma (1 paper, 2015). "MMP-2 and MMP-9 expression was reported as a characteristic for pleural malignant mesothelioma, and particularly MMP-2 was suggested as a predictive marker for poor prognosis." (PMID 26078352, 2015).
pneumococcal infection (1 paper, 2018). Infections with bacteria of the species streptococcus pneumoniae. "Increased susceptibility to pneumococcal infection was described for MMP2 and MMP9 double knockout mice." (PMID 29119707, 2018). "When we analyzed the expression of these and other MMPs, we observed that the pneumococcal infection indeed induced the expression of MMP‐2, MMP‐3, MMP‐8 and pro‐MMP9 in the respiratory tract of AIRmax mice." (PMID 29119707, 2018). "Conversely, pneumococcal infection did not induce the expression of MMP‐2 and MMP‐3 in AIRmin mice, not even at 48 h post‐challenge, when high numbers of bacteria were observed." (PMID 29119707, 2018).
polycystic ovary syndrome (1 paper, 2014). A disorder that manifests as multiple cysts on the ovaries. "Gelatinase activity by MMP-2 is found in follicular fluid on the inside of the follicle and higher activity is found in PolyCystic Ovary Syndrome (PCOS) patients compared to women with normal ovulation." (PMID 24485069, 2014).
pouchitis (1 paper, 2025). Acute inflammation in the intestinal mucosa of the continent ileal reservoir (or pouch) in patients who have undergone ileostomy and restorative proctocolectomy (proctocolectomy, restorative). "Its use has been shown to decrease inflammatory markers, including TNF-α, IFN-γ, and MMP-2/9, in patients with pouchitis." (PMID 40824057, 2025).
pregnancy hypertension (1 paper, 2023). "Hence, the balanced activity of MMP-2 may be necessary for maintaining normal vascular tone, including in normotensive pregnancy, while the dysregulated activity of MMP-2 has been associated with vascular dysfunction in pregnancy hypertension." (PMID 37628999, 2023).
pressure ulcers (1 paper, 2021). "Similar to mupirocin, mice treated with oral clindamycin exhibited a decrease in expression of IL-1β (−1.32-fold change), MMP-2 (−1.37-fold change), and TNF-α (−2.80-fold change) in infected pressure ulcers." (PMID 34035383, 2021).
primary aldosteronism (1 paper, 2020). An endocrine disorder characterized by excessive production of aldosterone by the adrenal glands. "With regard to serum MMP-2, in most previous research, a similar positive association of MMP-2 levels with LA volume was observed, although smaller studies and/or performed in patients with primary aldosteronism did not observe this association." (PMID 32668720, 2020).
primary lymphedema (1 paper, 2024). A congenital condition that results in swelling in the arms or legs, and can occur during adolescence or adulthood. "It was shown that, in primary lymphedema, genotypes associated with low MMP2 and TIMP2 in serum and tissue fluid are detected, while in secondary lymphedema, other associations of the production levels with combined genetic traits are observed." (PMID 39027126, 2024). "Thus, in primary lymphedema, the most significant correlationsare revealed between MMP2 and the tissue inhibitorTIMP2 levels (OR = 0.703; p < 0.01), whereas the VEGF serumlevel is inversely correlated with the MMP3 serum level(OR = –0.629; p < 0.05)." (PMID 39027126, 2024).
protein losing enteropathies (1 paper, 2018). "In humans, to our knowledge, there has been so far no report studying MMP-2 and -9 activities in patients with protein losing enteropathies." (PMID 29530095, 2018).
Pseudomonas infection (1 paper, 2018). Infections with bacteria of the genus pseudomonas. "CBO exhibited a regulatory effect on CS-mediated activation of MMP-2 in chemically wounded 3T3L1 fibroblast cells, providing a new rationale for CBO-mediated control of Pseudomonas infections." (PMID 29467483, 2018).
Pulmonary hypoplasia (1 paper, 2013). "SHAM fetuses showed neither real pulmonary hypoplasia nor significant changes in elastin deposition, but sensitive qPCR could detect differences for TNC, TIMP2, and MMP2/TIMP1 ratio." (PMID 23840910, 2013).
pyoderma gangrenosum (1 paper, 2020). An idiopathic, rapidly evolving, and severely debilitating disease occurring most commonly in association with chronic ulcerative colitis. "Pyoderma gangrenosum and PASH HS lesions also exhibit overexpression of MMP-2 and MMP-9." (PMID 32973741, 2020).
rectal adenocarcinoma (1 paper, 2021). "After radiotherapy, MMP-2/-9 levels increased drastically within the rectal adenocarcinoma indicating a role of MMP-2/-9 for radioresistance." (PMID 34055644, 2021).
relapsing (1 paper, 2022). "A previous study exploring the role of MMPs in several neuromuscular conditions before and after IVIG treatment showed that baseline elevated levels of MMP-9 dropped after IVIG, while a post-treatment increase in MMP-2 levels could indicate a relapsing disease." (PMID 36358365, 2022).
renal adenocarcinoma (1 paper, 2023). "This study shows that the curcuminoid EF24 in combination with TRAIL increases peroxidase activity in the renal adenocarcinoma cell line ACHN, reducing the level of intracellular H2O2 and MMP-2/MMP-9 activity, a mechanism that is also observed after treatment with curcumin and TRAIL." (PMID 36674555, 2023).
renal hypertension (1 paper, 2016). Hypertension caused by the kidney's hormonal response to narrowing or occlusion of the renal arteries. "Seven of them (Agtr1a, Fn1, Gja1, Lama2, Mmp2, Mmp9, Nos3) are known as being associated with renal hypertension." (PMID 28105926, 2016). "The changes in expression of DEGs associated with renal hypertension (Agtr1a, Fn1, Gja1, Lama2, Mmp2, Mmp9, Nos3) may also be suggested to have a significant impact on disease development in ISIAH rats." (PMID 28105926, 2016).
retinal vein occlusion (1 paper, 2020). An occlusion of the retinal vein. "The AH concentrations of MMP-1, MMP-2, MMP-7, and MMP-9 are also elevated in patients with retinal vein occlusion." (PMID 32596291, 2020).
rheumatic diseases (1 paper, 2021). "Moreover, since DCN, CTSB and MMP2 also promote the inflammatory process in OA, reduction mediated by VIP again corroborates its well-known anti-inflammatory role in rheumatic diseases." (PMID 34208590, 2021).
Salmonella Infections (1 paper, 2023). Infections with bacteria of the genus SALMONELLA. "We used quantitative real-time PCR (qPCR) to determine the expression level of mmp-2, mmp-9 and e-cadherin in HCT116 cells during Salmonella infection and found that the expression level of mmp-2 and e-cadherin decreased, while the expression level of mmp-9 increased significantly." (PMID 36812247, 2023).
sarcoidosis (1 paper, 2023). Sarcoidosis is a multisystemic disorder of unknown cause characterized by the formation of immune granulomas in involved organs. "Previous studies have demonstrated the contribution of gelatinase MMP-2 and MMP-9 in cell migration, and we explored the role of MMP-9 in macrophage recruitment in GA and sarcoidosis." (PMID 36959923, 2023).
senile cataract (1 paper, 2018). A cataract with no obvious cause occurring in persons over 50 years old. "We found that the concentrations of IL-8, MMP-2, MMP-3, MMP-9, TGFβ-1, TGFβ-2, TGFβ-3, SAA, and TNF-α were significantly elevated in JIAU samples compared with the control group (senile cataract patients)." (PMID 29675026, 2018).
septic shock (1 paper, 2018). Shock caused by infection; frequently caused by gram negative bacteria, although some cases have been caused by other bacteria, viruses, fungi, and protozoa; characterized by fever, chills, tachycardia, tachypnea, and hypotension. "The expression and activity of MMP-2 and MMP-9 was examined in patients with septic shock by FC and using a 3 compartment model (plasma, intraplatelet and platelet membrane) by gelatin zymography." (PMID 29734352, 2018).
skin infection (1 paper, 2024). An inflammatory process affecting the skin, caused by bacteria, viruses, parasites, or fungi. "MMP2 plays a critical role in tissue remodeling and repair, and it has been identified as a hub gene in various processes such as skin infection, skeletal development, and cardiac remodeling." (PMID 39518808, 2024).
small vessel stroke (1 paper, 2024). "Similarly, some people found low methylation levels of MMP-2 are associated with small-vessel stroke in men, and AHCY gene methylation was significantly higher in IS than in control in both men and women or in different age groups." (PMID 39239108, 2024). "MMP-2 methylation levels in peripheral blood DNA have been shown to be significantly lower in patients with small-vessel stroke, especially in men, than in controls, possibly related to the possible role of MMP-2 in disruption of the blood–brain barrier due to insufficient perfusion of brain tissue." (PMID 39239108, 2024).
spider veins (1 paper, 2017). "Finally, local transdermal application of Magnolol attenuated pressure-mediated development of varicose/spider veins in mice and was accompanied by the absence of proliferating and MMP-2 positive endothelial cells." (PMID 29259201, 2017).